PRLR (prolactin receptor)
Diseases named in the same sentence as PRLR in open-access papers (continued):
Sharing a sentence is not in itself a finding about the gene and the disease.
breast cancer (continued). "Clarifying PRL/PRLR roles in breast cancer will require advanced studies, including genetically engineered models for more precise investigation." (PMID 41370498, 2025). "Overall, our results highlight that promoting PRL/PRLR signaling while inhibiting the YAP-CCN2 oncogenic pathway as a differentiation-based therapeutic opportunity in breast cancer with potential merit in other cancers." (PMID 40157909, 2025). "The identification of exon 11 of PRLR led to the discovery of alternative spliced products and two novel short forms (SF) that can inhibit the long form (LF) of PRLr activity, which is relevant in physiological regulation and breast cancer." (PMID 40160874, 2025). "PRLr was found to be an independent predictor of favorable prognosis in human breast cancer patients." (PMID 40160874, 2025). "Altogether, these results highlight that in mammary and breast cancer cells, the pro-differentiation effects of PRL/PRLR are closely linked to Hippo pathway promoting cell polarity and luminal linage differentiation." (PMID 40157909, 2025). "Our previous results emphasized PRL/PRLR pathway as a promoter of differentiation in breast cancer cells driving favorable patient outcomes." (PMID 40157909, 2025). "In spite of this, AEA has been previously reported to mediate CB1R-dependent downregulation of PRLR in breast cancer cells, thus rendering them insensitive to the mitogenic action of PRL." (PMID 38184644, 2024). "In summary, these findings identified the paralleled expression pattern between PRLR and ERα in breast cancer." (PMID 38898487, 2024). "For example, PRLR is highly expressed in a subset of human breast cancer and prostate cancer, which makes it a potential target for cancer treatment." (PMID 37490712, 2023). "The reduced phosphorylation of PRLR in phospho-degron results in inefficient recruitment of β-TrCP and the accumulation of PRLR in breast cancer cells and tissues." (PMID 37686524, 2023). "Targeting PRLR has been reported to exert anticancer effects on breast cancer cells both in vitro and in xenograft models." (PMID 37686524, 2023). "The amplification of the epidermal growth factor (EGF) receptor (EGFR), HER2, as well as PRLR in breast cancers, has been regarded to accelerate tumor growth by activating their downstream signaling pathways." (PMID 37415164, 2023). "The stabilization of the prolactin receptor (PRLR) is also correlated with enhanced expression of it in breast cancer." (PMID 37686524, 2023). "Increased membrane ruffling, cell motility, and cytoskeletal changes were consequences of PRLR activation in breast cancer cells." (PMID 36945262, 2023). "In a study conducted by Ashley Sutherland, the researchers investigated the levels of prolactin receptor (PRLR) using quantitative immunohistochemistry in 134 primary breast cancer samples and matched samples of 17 primary breast cancer and bone metastasis." (PMID 38041134, 2023). "The EC50 values of PRLR-DbsAb against breast cancer cell lines MDA-MB-231, MCF-7, SKBR-3, and T47D were found to be 5.053, 1.78, 46.68, and 7.63 ng/ml, respectively." (PMID 36714582, 2022). "PRL/PRLR and E2/ER synergistically can regulate the gene expression and proliferation of breast cancer cells." (PMID 36187116, 2022). "Using flow activated cell sorting, the authors demonstrated that LFA102 binds to PRLR in human breast cancer cell lines, in addition to primary breast cancer cells." (PMID 36714582, 2022). "This review also stresses the importance of signal transduction pathways (PI3K/AKT, RAF/MEK/ERK, FAK, and SFK) activated by PRL/PRLR in breast cancer." (PMID 36187116, 2022). "PRLR signaling can also induce motility and invasion of T47D breast cancer cells by activating downstream effectors such as TEC and NEK3 kinases, thus leading to cytoskeletal and focal adhesion reorganization." (PMID 36187116, 2022).
breast cancer (continued). "We have summarized how steroid hormones (E2 and PR) and growth factors (EGF/ERBB1 and HER2) can induce the transcription of PRLR, thereby increasing its expression in breast cancer cells and promoting cell proliferation." (PMID 36187116, 2022). "Several groups have studied the role of PRLR in breast cancer, and in the process have observed antagonistic activity in cells treated with the G129R-hPRL analog." (PMID 36714582, 2022). "Altogether, there is now a large body of evidence implicating PRL/PRLR pathway as a clinically relevant anti-tumorigenic pathway in breast cancer." (PMID 36157462, 2022). "The prolactin receptor (PRLR) is expressed in a subset of breast cancers, and even at relatively low levels of expression, is constitutively internalised and rapidly trafficked to lysosomes for degradation, thus serving as a good therapeutic target for an ADC." (PMID 36046842, 2022). "PRLR is highly expressed in many breast cancers across all different subtypes, and epidemiologic analyses and experimental studies are revealing that PRL can elicit both pro-differentiation and pro-aggression outcomes." (PMID 35784527, 2022). "The long form (LF) of PRLR with 610 aa was isolated from human hepatoma and breast cancer cells and from the rat ovary." (PMID 36187116, 2022). "Previous reports have examined PRLR expression and have reported a widespread expression in breast cancer samples." (PMID 36157462, 2022). "PRLR activation induces JAK/STAT and mitogen-activated protein kinase signaling pathways implicated in the development of mammary glands and etiology of breast cancer." (PMID 36187116, 2022). "LFA102 treatment (300 mg/kg) significantly reduced PRLR signaling and tumor growth in this rat mammary cancer model as a monotherapy and combination with letrozole (aromatase inhibitor, 10 μg/kg)." (PMID 36714582, 2022). "Mouse PRL has little activity at the human PRLR, which has complicated experimental study of breast cancers in vivo." (PMID 35784527, 2022). "The identification of exon 11 of PRLR led to finding of alternative spliced products and two novel short forms (SF) that can inhibit the long form (LF) of PRLR activity with relevance in physiological regulation and breast cancer." (PMID 36187116, 2022). "An autocrine/paracrine loop increases PRLR mRNA expression via its ligand PRL in breast cancer cells." (PMID 36187116, 2022). "More recent findings contradict these observations and implicate that PRLR expression is generally downregulated in breast cancer." (PMID 36157462, 2022). "Targeting CDK7 kinase, which is known to regulate both transcription and the cell cycle, and ERα phosphorylation with the THZ1 inhibitor was found to effectively inhibit the transcription of PRLR and cell migration in breast cancer cells." (PMID 36187116, 2022). "Additional studies are needed to better understand the role of alternatively spliced PRLR isoforms and the manner in which such splicing is regulated in breast cancer." (PMID 36187116, 2022). "Assessing the expression levels of PRLR in breast cancer cases is vital to further define the role of PRL in breast cancer." (PMID 36157462, 2022). "REGN2878-DM1 was further tested in breast cancer mouse xenografts of T47Dv11, which exhibit high levels of endogenous PRLR." (PMID 36714582, 2022). "The full length “long” PRLR isoform is best studied, but expression of the “intermediate” PRLR isoform in breast cancers is also recognized." (PMID 35784527, 2022). "The various regulatory modalities contributing to the upregulation of PRLR provide options for the development of therapeutic approaches to mitigate its participation in breast cancer progression and resistance." (PMID 36187116, 2022). "We previously used human breast cancer cases organized in tissue microarrays as well as bioinformatics analyses and datasets to assess the expression of PRLR in breast cancer." (PMID 36157462, 2022).
breast cancer (continued). "The expression of bone homing inductors of the circulating breast cancer cells, also identified as bone metastasis markers in breast cancer, such as Versican, Osteopontin, and Prolactin receptor, were investigated." (PMID 36499741, 2022). "In the case of PRLR, only a few attempts have successfully developed a potential therapeutic small molecule inhibitor or monoclonal antibody (LFA102) to block PRLR signaling induced cell proliferation in breast cancer cell lines." (PMID 36187116, 2022). "Most recent and indeed direct approach was the generation of humanized antibodies to block PRLR as a targeted therapy in breast cancer." (PMID 36157462, 2022). "Apart from the signalling interaction between ER and PRL pathway, the oestradiol–ER complex has been reported to transcriptionally upregulate both prolactin and PRLR in breast cancer." (PMID 35448537, 2022). "On the other hand, loss of expression of the PRLR in ER+ and HER2-E breast cancer cells resulted in the enrichment of these BCSC populations." (PMID 36157462, 2022). "Owing to the positive effect of estrogen on PRLR transcription, this reciprocal regulation amplifies both ER and PRLR signaling in breast cancer." (PMID 36187116, 2022). "Studies in breast cancer cells demonstrated that the transcription of PRLR was directed by the preferentially utilized PIII promoter, which lacks an estrogen responsive element." (PMID 36187116, 2022). "This preclinical study demonstrates the application of dual GHR/PRLR antibodies as a useful strategy for the treatment of breast cancer by impeding the PRLR signaling axis." (PMID 36714582, 2022). "These isoforms have further confounded detection of PRLR across breast cancer subtypes, which is already complicated by the specificity and sensitivity of historically available antibodies." (PMID 35784527, 2022). "Mechanistically, PRLR-DbsAb was found to recruit T cells to PRLR expressing T47D breast cancer cells, which further induced cytotoxicity." (PMID 36714582, 2022). "HOXA1-mediated upregulation of PRLR (prolactin receptors) and their subsequent signal transduction is another important mechanism demonstrated in the oncogenic transformation of mammary carcinoma cells." (PMID 34617205, 2022). "Next, we assessed the effects of loss of PRLR expression in modulating HER2 expression levels, the biomarker of HER2-E breast cancer subtype." (PMID 33446633, 2021). "hPRLrI, initially cloned from breast cancer patient samples and named for its resemblance to the intermediate rat PRLr, is generated by an out-of-frame splicing event." (PMID 33772010, 2021). "The functional attributes and tumor expression profile of PRLR make it an attractive target for therapeutic intervention in breast cancer and potentially other malignancies." (PMID 34107902, 2021). "Due to the wide expression of PRLR in almost all types of breast cancers, fusion protein MICA-G129R can be used for many types of breast cancers regardless the common classification with ER, PR, HER2 or triple negative breast cancers." (PMID 34077462, 2021). "A marked and heterogenous elevation in PRLR was previously reported in other types of tumors including breast cancer, prostate cancer, hepatocellular carcinoma and glioblastoma multiforme." (PMID 34358244, 2021). "Fusion protein MICA-G129R was confirmed not only able to bind to PRLR-positive breast cancer cells and NK cells, but also enhance cytotoxicity of NK cells on PRLR-positive cells." (PMID 34077462, 2021). "The expression levels of PRL and PRLR in breast cancer cells and breast cancer tissues are elevated in most ER+ and ER− tumours." (PMID 34651424, 2021). "One of the limitations of this study is that T47D was the only cell lines used, so more breast cancer cell lines with different PRLR expression levels will be included in future study." (PMID 34077462, 2021).
breast cancer (continued). "Human GH is also able to bind to the prolactin receptor (PRLr), whose signaling can modulate proliferation, survival, motility, angiogenesis, and differentiation in breast cancer." (PMID 34206988, 2021). "Prolactin receptor (PRLR) is an attractive antibody therapeutic target with expression across a broad population of breast cancers." (PMID 34107902, 2021). "The PRLR/PRL (prolactin ligand) signaling axis contributes to estrogen-insensitive breast cancer growth and development." (PMID 34107902, 2021). "The in vivo interaction of human NK cells and MICA-G129R can be investigated in immunodeficiency mice xenografted with human PRLR-positive breast cancer cells." (PMID 34077462, 2021). "Altogether, these results emphasize that maintaining the expression of PRLR in HER2-E breast cancer subtype abrogates stemness and aggressive tumorigenic features by ensuring combined luminal and epithelial differentiation." (PMID 33446633, 2021). "Breast cancer cells were reported to up-regulate human prolactin receptor (PRLR) to assist their growth through the utilization of prolactin (PRL) as the growth factor, which makes PRLR a potential therapeutic target for breast cancer." (PMID 34077462, 2021). "h16f-MMAE and ABBV-176 conjugates were evaluated for their ability to inhibit the growth of a panel of 25 breast cancer cell lines expressing different levels of PRLR." (PMID 34107902, 2021). "When binding to PRLR, the fusion protein labels the breast cancer cells with MICA, which attracts and activates NK cells to kill the breast cancer cells." (PMID 34077462, 2021). "PRL/PRLR can substantially promote migration and invasion of T47D breast cancer cells by activating alternate downstream effectors like TEC and NEK3 kinases, leading to cytoskeletal and focal adhesion rearrangements necessary for cell adhesion and migration." (PMID 34572912, 2021). "Some clinical studies have highlighted that the expression of PRLR can be used as a favorable prognostic marker for benign breast tumors and aggressive type of luminal breast cancer." (PMID 34572912, 2021). "Conversely, a decrease in PRLr levels achieved by either pharmacological or genetic means in human breast cancer cells dramatically reduces the transformation and tumorigenic properties of these cells." (PMID 34206988, 2021). "For example, the neutralizing antibody LFA-102 antagonizes PRLR signaling and proliferation in breast cancer cells and regresses PRL-dependent tumor xenografts." (PMID 34107902, 2021). "PRLR signaling enhances breast cancer cell motility by regulating actin cytoskeleton rearrangement which involves phosphorylation of c-SRC, moesin, and FAK kinases by PRL." (PMID 34572912, 2021). "PRL in breast cancer cells via PRLR/JAK2 can also induce phosphorylation of ERBB2/HER2, which in turn activates the downstream RAS/MEK/ERK pathway required for ERα phosphorylation." (PMID 34572912, 2021). "An NIH study showed that the ratio of PRLR-SF to PRLR-LF was significantly decreased in 76% of breast cancer patients." (PMID 33664869, 2021). "PRLR is involved in the activation of MAPK/ERK signaling in several breast cancer cell lines, which mediate PRL-induced biological activity in these cells." (PMID 34572912, 2021). "Here, using CRISPR/Cas9 technology, we interfered with expression of the PRLR in two different breast cancer cell model systems representative of the two luminal/epithelial breast cancer subtypes HR+ (MCF-7 cells) and HER2-E (SKBR-3 cells)." (PMID 33446633, 2021). "PRLR is a receptor whose expression is enhanced in breast cancers and presents a potential target for delivering cytotoxic payloads independent of ER, PR or HER2 dependence/expression." (PMID 34107902, 2021). "Collectively, these results demonstrate that expression of PRLR in breast cancer derives and supports luminal and epithelial differentiation, guarding against aggressive tumor behavior." (PMID 33446633, 2021).
breast cancer (continued). "Together these results indicate that PRLR expression modulates breast cancer stemness in a subtype context-dependent manner and acts as a safeguard against enrichment of these aggressive BCSC populations in both HR+ and HER-2E molecular subtypes." (PMID 33446633, 2021). "The role of PRLR in the etiology and proliferation of breast carcinoma induced by prolactin (PRL) has been well established." (PMID 34572912, 2021). "Prospective studies reveal up to 95% of female breast tumors, and 60% of male breast carcinomas express high levels of PRLR." (PMID 34572912, 2021). "E2/ERα has been reported to combine with C/EBPβ/SP1 and induce transcriptional activation of the generic hPIII promoter, activating PRLR expression in MCF-7 breast cancer cells." (PMID 33173437, 2020). "In this case, it is necessary to develop the dual-function GHR/PRLR antagonists with anti-breast cancer potential." (PMID 33362552, 2020). "Human NEK3 appears to play an important role in prolactin receptor signaling, specifically in a pathway that contributes to the progression of breast cancer and increases the motility of breast cancer cells in vitro." (PMID 31906878, 2020). "PRLR-DbsAb increases cytotoxicity in all breast cancer cells with different PRLR-expression compared to control PRLR mAb group." (PMID 32398042, 2020). "It was shown that the positive expression of PRLR in breast cancer tissues was significantly higher than that in adjacent tissues similar to normal breast tissues." (PMID 32398042, 2020). "The best killing activities of PRLR-DbsAb to different breast cancer cell lines T47D, SKBR-3, MCF-7 and MDA-MB-231 were 56.42%, 46.92%, 36.54% and 34.55% respectively with the EC50 all being ng/ml scale." (PMID 32398042, 2020). "Dysregulated PRL/PRLR or GH/GHR activity has been associated with the development of various cancers, including breast cancer." (PMID 33362552, 2020). "Multiple studies suggest that PRL and GH promotes breast cancer growth, leading to wide interest in PRLR/GHR as a potential target for breast cancer therapy." (PMID 33362552, 2020). "In vitro PRLR-DbsAb efficiently inhibited the growth of breast cancer cells with high PRLR expression, accompanied with T cell activation and cytokines release." (PMID 32398042, 2020). "We also observed an increase in PRLR-positive breast cancer samples as tumor grades increased including pathological grade, clinical or N stage." (PMID 32398042, 2020). "Prolactin receptor (PRLR) is highly expressed in a subset of human breast cancer and prostate cancer, which makes it a potential target for cancer treatment." (PMID 32398042, 2020). "A PRLR blocking monoclonal antibody showed significant antitumor activity against MCF7 breast cancer xenografts." (PMID 32121009, 2020). "The prolactin/PRLR-signaling axis has been consistently shown to play a permissive role in the development of primary breast carcinomas and distant metastatic lesions." (PMID 33335078, 2020). "For example, the bispecific antibody simultaneously targets the HER2 and PRLR double positive (HER2+/PRLR+) breast cancer cells to enhance the internalization and activity of the ADC, and to decrease the off-target toxicities to the healthy cells." (PMID 31068807, 2019). "The results showed that concomitant PRLR expression with TGFβ receptors in breast cancer clinical samples was significantly downregulated in cancer samples compared to normal/benign tissue." (PMID 30987013, 2019). "This association between the preservation of higher levels of the PRLR/TGFβRI/TGFβRII gene signature reached statistical significance in HER-2 as well as luminal B breast cancer subtypes." (PMID 30987013, 2019). "Earlier studies using a panel of normal breast and breast cancer cases examined the expression of PRLR as well as TGFβRI and TGFβRII individually." (PMID 30987013, 2019).